SLC22A12 (solute carrier family 22 member 12)
Diseases named in the same sentence as SLC22A12 in open-access papers (continued):
Sharing a sentence is not in itself a finding about the gene and the disease.
kidney cancer (2 papers, 2021 to 2022). Primary or metastatic malignant neoplasm involving the kidney. "Generally, these results collectively indicate that SLC22A12 is under-expressed in kidney cancer cells." (PMID 34249694, 2021). "A number of the identified transporters (e.g., SLC22A12/URAT1, SLC22A6/OAT1, SLC22A8/OAT3, ABCG2) are well-established uric acid transporters; this may be clinically important since a number of studies indicate that altered uric acid levels and kidney cancer are associated." (PMID 36230695, 2022). "We found that Solute Carrier Family 22 Member 12 (SLC22A12), a tissue-specific gene, played an important role in the occurrence and development of kidney cancer." (PMID 34249694, 2021).
periodontitis (2 papers, 2022 to 2023). An acute or chronic inflammatory process that affects the tissues that surround and support the teeth. "Moreover, it should be noted that some urate transporters (SLC2A9 and SLC22A12) showed increased gene expressions in gingival tissues from periodontitis patients, which could be a potential contributor or confounder for an altered UA concentration in periodontal pockets." (PMID 36973692, 2023).
renal cell carcinoma (2 papers, 2022 to 2023). "Before discussing the SLC22 genes identified in this study in relation to renal cell cancer and various oncologic variables (TNM class) used to determine pathologic stage, we note previous work has shown that SLC22A2, SLC22A12, and SLC22A13 are downregulated in human kidney tumors." (PMID 36230695, 2022).
Clear Cell Renal Cell Carcinoma (1 paper, 2021). "Conclusively, SLC22A12 may be a potential diagnostic biomarker for clear cell renal cell carcinoma." (PMID 34249694, 2021).
Fanconi syndrome (1 paper, 2019). "We performed comprehensive genetic analysis, including that for SLC22A12 encoding URAT1 and SLC2A9 encoding GLUT9, which are genes causing RHUC, and SLC34A1, EHHADH, HNF4A, and SLC2A2, which are genes causing Fanconi syndrome; however, the results could not identify the responsible mutation." (PMID 31771519, 2019).
Generalized arterial calcification of infancy (1 paper, 2025). "The most common KSD-associated VUS were sucrase-isomaltase deficiency (SI, N = 8), Wilson disease (ATP7B, N = 7), pseudoxanthoma elasticum and generalized arterial calcification of infancy (ABCC6, N = 5), CYP24A1-related hypercalcemia (CYP24A1, N = 4), and hypouricemia Renal 1 (SLC22A12, N = 4)." (PMID 40126616, 2025).
Kidney Chromophobe (1 paper, 2021). "Apart from that, SLC22A12 was only expressed in the kidney (KIRC: Kidney renal clear cell carcinoma; KIRP: Kidney renal papillary cell carcinoma; KICH: Kidney Chromophobe)." (PMID 34249694, 2021).
renal carcinoma (1 paper, 2021). A carcinoma arising from the epithelium of the renal parenchyma or the renal pelvis. "RCC cell lines were transfected with SLC22A12 plasmid or si-SLC22A12 to investigate the function of SLC22A12 on the pathobiology of renal cancer." (PMID 34249694, 2021). "Furthermore, SLC22A12 over-expression in vitro inhibited the proliferation, migration, and invasion of renal cancer cells by regulating PI3K/Akt pathways." (PMID 34249694, 2021).
sarcoma (1 paper, 2021). A usually aggressive malignant neoplasm of the soft tissue or bone. "No other cancer transcriptome profile included SLC22A12, except for two sarcoma samples (SARC)." (PMID 34249694, 2021).
xanthinuria (1 paper, 2025). A metabolic metabolic disorder characterized by excess urinary excretion of the purine base xanthine. "Disorders of uric acid metabolism had 12 genetic results on xanthinuria (XDH and MOCOS) and renal hyperuricemia (SLC22A12) genes, affecting 11 patients (10%)." (PMID 40126616, 2025).
cancer (6 papers, 2020 to 2023). A tumor composed of atypical neoplastic, often pleomorphic cells that invade other tissues. "In our previous study, approximately 90% of hypouricemia patients showed two variants in SLC22A12, p.W258* and p.Arg90His, in two independent cohorts, the Korean Genome and Epidemiology Study (KoGES, n = 179,318) and the Korean Cancer Prevention Study (KCPS-II, n = 156,701)." (PMID 34572357, 2021). "Our previous study showed that two recessive variants of SLC22A12 (p.Trp258*, pArg90His) were identified in 90% of the hypouricemia patients from two independent cohorts: the Korean genome and epidemiology study (KoGES) and the Korean Cancer Prevention Study (KCPS-II)." (PMID 34572357, 2021). "Because these are transporters of endogenous metabolites and drugs—and, in the case of SLC22A6, SLC22A8, SLC22A12, established drug targets—these observations are of interest from both the viewpoint of cancer biology and therapeutics." (PMID 36230695, 2022). "Data of SLC22A12 mRNA expression levels in ccRCC tissues and para-cancer tissues were downloaded from the TCGA database to understand the role of SLC22A12 expression in tumorigenesis." (PMID 34249694, 2021). "The results suggest that SLC22A12 expression in tumor tissues was significantly lower than in para-cancer tissues." (PMID 34249694, 2021). "Additionally, qRT-PCR assay, immunoblotting test (IBT), and immunohistochemical (IHC) analyses of cancer tissues/cells and the corresponding normal controls verified that SLC22A12 is downregulated in ccRCC." (PMID 34249694, 2021). "Furthermore, IHC results from cancer/para-cancer pairs suggest that SLC22A12 was primarily located in the plasma membranes of both cancer and normal renal tubular epithelial cells; however, it was down-regulated in cancer cells." (PMID 34249694, 2021).
tumor (5 papers, 2018 to 2025). "SLC22A12 is DE between KIRC tumors and normal kidney, associated with overall survival in KIRC and DE between tumor size and progression (T3 vs. T4), stage I v II, and presence of metastasis (M0 vs. M1)." (PMID 36230695, 2022). "Gene set enrichment analysis (GSEA) showed that SLC22A12 expression levels are related to metabolism, cell cycle, and tumor-related signaling pathways." (PMID 34249694, 2021). "Altogether, SLC22A12 may interact with these proteins that regulate tumor cell homeostasis, thereby affecting cell proliferation, invasion, and migration." (PMID 34249694, 2021). "In summary, SLC22A12 may affect tumor progression and metastasis by affecting its cellular homeostasis." (PMID 34249694, 2021). "In summary, as a transporter for many vital metabolites, SLC22A12 may affect tumor cell survival through its impacts on the mentioned metabolites." (PMID 34249694, 2021). "More typically, hypouricemia is associated with high fractional excretion of uric acid due to genetic causes; including mutations in genes such as SLC22A12 (URAT1) and SLC2A9 (GLUT9) or factors such as uricosuric usage, renal tubulopathy, neoplasias, and other conditions." (PMID 29904633, 2018). "SLC22A12 downregulation may impact cellular homeostasis, altering the survival of the tumor cells." (PMID 34249694, 2021). "Five of those are found in comparisons of both tumor types: SLC22A6/OAT1, SLC22A7/OAT2, SLC22A8/OAT3, SLC22A12/URAT1, SLC22A13/ORCTL3." (PMID 36230695, 2022). "In KIRC, the stratification of patient data by pathological tumor characteristics revealed the importance of SLC22A2, SLC22A6, and SLC22A12 in disease progression." (PMID 36230695, 2022). "While multiple comparisons had no DE genes in the entire expressed gene list (i.e., Stage III vs. Stage IV), there were 6 DE SLC22 genes in the Tumor Size and Progression comparison in KIRC [SLC22A2, SLC22A5, SLC22A6, SLC22A11, SLC22A12, SLC22A18] (T3 v T4)." (PMID 36230695, 2022). "Collectively, these results provide us with solid evidence suggesting that SLC22A12 suppresses RCC cell proliferation, migration, and invasion, which play an essential role in tumor metastasis." (PMID 34249694, 2021). "SLC22A12 (aka URAT1) is, additionally, best known as a kidney transporter of urate, an antioxidant, which may be relevant to tumor behavior." (PMID 36230695, 2022). "Second, we have not thoroughly studied the mechanism by which SLC22A12 exerts its tumor suppressor effect." (PMID 34249694, 2021). "First, we only verified the anti-tumor effect of SLC22A12 through in silico and in vitro experiments, without relevant in vivo data." (PMID 34249694, 2021).
inflammation (1 paper, 2020). Aberrant reaction of the microcirculation characterized by movement of fluid and leukocytes from the blood into extravascular tissues. "Oct1-3 (Slc22a1-3), Octn1 (Slc22a4), Oat1, Oat3 and Rst (Slc22a12) knockout (KO) mice are fertile, viable and show no general phenotypic abnormalities except for the Oat3 KO’s decreased blood pressure, serum metabolite changes, and the Octn1 KO’s increased susceptibility to intestinal inflammation." (PMID 32183456, 2020).
SLC22A12 also shares sentences with these, for which no sentence is quoted: Obesity (14 papers); diabetes (8); Hypertension (7); chronic kidney disease (6); kidney damage (6); Hypercholesterolemia (4); renal fibrosis (4); urolithiasis (4); endothelial dysfunction (3); Hepatic steatosis (3); metabolic disorders (3); atherosclerosis (2); Cardiovascular Disease (2); cystic kidney disease (2); genetic disorder (2); kidney diseases (2); Renal insufficiency (2); type 2 diabetes (2); abdominal aortic aneurysm (1); atrial fibrillation (1); breast carcinoma (1); carnitine deficiency (1); chronic heart failure (1); ciliopathies (1); congenital disorder of glycosylation (1); coronary atherosclerosis (1); depression (1); diabetic kidney disease (1); distal renal tubular acidosis (1); glucosuria (1).
A further 27 diseases each share a sentence with SLC22A12 in 1 paper.